CD36 (CD36 molecule (CD36 blood group))
Diseases named in the same sentence as CD36 in open-access papers (continued):
Sharing a sentence is not in itself a finding about the gene and the disease.
glioma (20 papers, 2010 to 2025). A benign or malignant brain and spinal cord tumor that arises from glial cells (astrocytes, oligodendrocytes, ependymal cells). "Elevated levels of CD36 in glioma stem cells have been linked to enhanced proliferative abilities and faster tumor progression within living organisms." (PMID 39691192, 2024). "The second most perturbed gene in gliomas is CD36, which encodes a putative fatty acid transporter." (PMID 31169500, 2019). "Collectively, these findings suggest that CD36 acts as a context-dependent prognostic biomarker, exerting tumor-promoting effects in certain malignancies such as glioma, breast, and renal cancers." (PMID 41550652, 2025). "Third, since CD36 is also expressed in glioma stem cells and endothelial cells, specifically targeting CD36 in TAMs would provide stronger evidence for our findings." (PMID 39691192, 2024). "Our current work extends previous findings that upregulated the expression of CD36 enhanced the phagocytic activity of TAMs that more GFP glioma cells were engulfed, after CB2R activation." (PMID 39691192, 2024). "The potential impact of CB2R activation on CD36 expression within glioma and endothelial cells is yet to be identified, which needs further investigation." (PMID 39691192, 2024). "This preference comports with another study demonstrating that glioma stem cells have increased levels of the FA scavenger receptor CD36 on their surface." (PMID 36594473, 2023). "In this study, CD36 expression was upregulated on glioma stem cell populations, which promoted enhanced self-renewal capacities and enhanced tumor growth in vivo." (PMID 36594473, 2023). "CD36 is reported to have an increased expression in glioma cancer stem cells (CSC), along with integrin alpha 6 and CD133, previously known as CSC markers." (PMID 35054787, 2022). "All the considered patient-derived cell lines were negative for the expression of angiogenic cell markers such as CD31 and CD36, which have been previously found also on glioma cancer stem cells." (PMID 36568177, 2022). "In CSCs, the elevated expression of CD36 was found and the uptake of an oxidized phospholipid, the ligand of CD36 drives glioma CSC proliferation, suggesting that the expression of CD36 is associated with CSC progression." (PMID 34348794, 2021). "The combined expression of CD36/CD44/CD133/ITGA6 was found to be a signature of glioma neurospheres from different sources and to be a marker of worse prognosis in patients." (PMID 31661927, 2019). "To investigate whether CD36 mediates the CB2R-induced phagocytic activity of TAMs in glioma, we sorted CD11b-positive TAMs using flow cytometry and examined the expression of CD36 in each group." (PMID 39691192, 2024). "Therefore, CB2R activation induced CD36 upregulation mediated the TAMs-mediated phagocytosis in glioma." (PMID 39691192, 2024). "CD36 is highly expressed in gliomas and has been related to tumor progression." (PMID 37612627, 2023). "Noting the fact that cancer stem cells have a high expression of CD36 and increased polyunsaturated fatty acid levels, this scavenger receptor could be related to a self-renewal and survival mechanism of glioma cells." (PMID 35054787, 2022). "In a glioma orthotopic tumor model, a CD36-targeting NIR fluorescent probe was developed to visualize the CD36 protein and delineate tumor boundaries, expanding the toolbox for surgical navigation." (PMID 40508051, 2025). "ELF4 is elevated in high grade gliomas, particularly in glioma and neuronal stem cell markers, including CD44, CD36, CD15, CD70, S100A4, and ALDH1A3." (PMID 38539424, 2024). "Of these PA transporters, FAT/CD36 and FABP5 are highly correlated with decreased glioma patient survival, and both are expressed at significantly higher levels in IDHwt tumors." (PMID 36012521, 2022).
glioma (continued). "THBS-1, a protein that inhibits angiogenesis by inducing apoptosis via activation of CD36 in microvascular endothelial cells, may be relevant to these mechanisms as well, as we found this pathway to be markedly upregulated in GBMs compared to lower grade gliomas." (PMID 20838435, 2010). "While not normally expressed in the brain, CD36 is a TIC marker in glioma, in which it promotes TIC-ness and drives progression." (PMID 31661927, 2019).
Glucose intolerance (20 papers, 2010 to 2026). Glucose intolerance (GI) can be defined as dysglycemia that comprises both prediabetes and diabetes. "On the contrary, the loss of Cd36 in mice leads to phenotypes such as lymphatic drainage, visceral fat, and glucose intolerance, which increases the risk for T2DM." (PMID 36157062, 2022). "Our study presents a pharmacogenetic interaction between limited genomic segment with mutated Cd36 gene and dexamethasone-induced glucose intolerance and triacylglycerol and cholesterol redistribution into lipoprotein fractions." (PMID 20398376, 2010). "In summary, we report a pharmacogenetic interaction between limited genomic segment with mutated Cd36 gene and dexamethasone-induced glucose intolerance and triacylglycerol and cholesterol redistribution into lipoprotein fractions." (PMID 20398376, 2010). "Thus, LEC CD36 optimizes lymphatic junctions and integrity of lymphatic lipid transport, and its loss in mice causes lymph leakage, visceral adiposity and glucose intolerance, phenotypes that increase risk of T2D." (PMID 34099721, 2021). "Later, we reported that a presence of defective Cd36/Fat-containing genomic segment substantially blunted DEX-induced glucose intolerance and dyslipidemia." (PMID 29731739, 2018). "Cd36−/− mice are acutely protected from HFD-induced glucose intolerance." (PMID 39503770, 2025). "However, HF feeding induced glucose intolerance and reduced insulin sensitivity were significantly improved by CD36 peptide treatment as demonstrated by GTT and ITT assays as well as reduced fasting plasma glucose and insulin levels from obese mice." (PMID 37980376, 2023). "Enhanced glucose tolerance and protection against glucose intolerance induced by high-fat diet (HFD; 60% fat, 7% sucrose) were observed in Cd36−/− mice vs WT mice, confirming earlier findings and ruling out environment- or breeding-related alterations." (PMID 39503770, 2025). "Even though CD36-depleted DR rats became as obese as DIO AAV controls, only DIO CD36 depleted rats became insulin-resistant on a 45% HFD as shown by a glucose intolerance and by elevated insulin levels during the oral glucose tolerance test." (PMID 31474875, 2019). "In addition, higher Cd36 expression level in SDG-P islets may participate in the acceleration of glucose intolerance under HFD feeding because CD36 protein (also known as fatty acid translocase) is postulated to facilitate fatty acid uptake, which leads to the attenuation of GSIS in β cells." (PMID 24454742, 2014).
hematoma (20 papers, 2015 to 2025). A hematoma is a collection of blood from a vascular structure into an extravascular space. "What’s more, the same study also found that patients with CD36 deficiency showed impaired hematoma resolution and poorer clinical outcome." (PMID 35237132, 2022). "Studies have shown that TNF-α downregulates the expression of microglia CD36, resulting in the loss of phagocytic capacity of microglia to phagocytosis of hematoma after intracerebral hemorrhage." (PMID 34956584, 2021). "The increase in CD36 expression in the perihematomal region is associated with faster hematoma clearance, and reduced CD36 expression increases the production of pro-inflammatory M1 macrophages/microglia mediators, such as TNF-α and IL-1β, thus inhibiting erythrophagocytosis and hematoma clearance." (PMID 35966018, 2022). "Activation of PPARγ or Nrf2enhances CD36 expression and erythrophagocytosis of microglia/macrophages,thereby promoting hematoma resolution and neurological recovery after ICH." (PMID 41504200, 2025). "Syk potentially mediates Th2-polarized cytokine secretion (Il-6/Il-10), Cd36 enhances hematoma resolution via Il-10/Stat3 signalling and Cd74 synergizes with MIF to amplify inflammatory cascades." (PMID 40623122, 2025). "Post-translational modifications, such asSUMOylation, can also enhance microglial CD36 expression and erythrophagocytosis,promote hematoma absorption and alleviate neurological deficits." (PMID 41504200, 2025). "Non-pharmacological interventions,including pulsed electromagnetic field therapy and remote ischemic conditioning(RIC), similarly promote hematoma resolution via CD36 modulation." (PMID 41504200, 2025). "CD36 knockout mice demonstrate delayed hematoma resolution and exacerbated deficits compared to wild-type (WT) mice post-ICH." (PMID 39660125, 2024). "Treatment with PPAR agonist (e.g. rosiglitazone) showed enhanced RBCs clearance by increasing CD36 expression and phagocytosis both in vitro and in vivo and in turn promoting hematoma resolution." (PMID 35832077, 2022). "Consistently, the upregulation of CD36 generates faster speed of erythrophagocytosis and hematoma resolution." (PMID 35237132, 2022). "For example, CD36 knock-out mice was found to have slower hematoma resolution and aggravated deficits when compared to wild-type mice after ICH." (PMID 35237132, 2022). "As M φ-mediated removal of erythrocytes is required for clot clearance, the roles and therapeutic values of CD36 in hematoma development has attracted considerable attention." (PMID 35237132, 2022). "Third, Nrf2 helps upregulate CD163 and CD36 expression in microglia; thus, we cannot exclude the possibility that the protective effect of albumin in promoting hematoma clearance is due to the contributions of other Nrf2 signaling pathways." (PMID 33708336, 2021). "In addition, our results show that Prdx1 can reduce the hematoma volume after ICH, its mechanism needs further study, we speculate that Prdx1 inhibits the release of inflammatory factors such as TNF-α, thereby promoting the expression of CD36 and causing the absorption of hematomas." (PMID 32210752, 2020). "Additionally, niacin facilitates the recruitment of M2-type microglia to the periventricular region, where they promote hematoma clearance via the CD36/CD163/HO-1 axis, reducing iron deposition and oxidative stress." (PMID 41205412, 2025). "Thesefindings suggest that activating the CD36-oxidized PtdSer pathway could provide atherapeutic strategy to enhance hematoma resolution after ICH." (PMID 41504200, 2025). "Upregulation of CD36 accelerates erythrophagocytosis and enhances hematoma resolution." (PMID 39660125, 2024). "Notably, studies have shown that increasing CD36 expression can influence microglia to induce the M2 phenotype surrounding hematoma, which enhances their phagocytosis and anti-inflammatory effects." (PMID 36970539, 2023).
hematoma (continued). "Therefore, we believe that upregulating CD36 after ICH can increase endogenous hematoma absorption; however, the precise mechanism and cell types involved remain to be investigated." (PMID 36970539, 2023). "In addition, microglia are the only cells specifically identified in ICH for the CD36-mediated clearance of hematoma components." (PMID 36970539, 2023). "Upregulation of CD36 expression was demonstrated in TLR-4 knockout mice suggested that TLR-4 suppression could promote hematoma resolution 49,55." (PMID 35832077, 2022). "In ICH, CD36-mediated apoptotic cells clearance is essential for hematoma resolution." (PMID 35237132, 2022). "In contrast, during the chronic recovery phase, “anti‐inflammatory” (M2‐type) microglia aid in hematoma resolution and tissue repair by phagocytosing cellular debris and engaging in receptor‐mediated clearance via CD163, CD36, and CD47." (PMID 40994248, 2025). "Enhancing microglial/macrophage erythrophagocytosis throughactivation of TAM receptors, CD36, and TREM2 or inhibition of theSIRPα-CD47 pathway plays a central role in promoting hematoma clearanceand mitigating secondary brain injury." (PMID 41504200, 2025). "Through HCAR2-dependent regulation of the CD36/CD163/HO-1 axis, niacin enhances M2 microglial phagocytosis, accelerates hematoma clearance, reduces hydrocephalus, and improves neurological outcomes while mitigating neuroinflammation and oxidative stress." (PMID 41205412, 2025). "In the present study, we demonstrate that CDNF enhances expression of the scavenger receptors, CD36 and CD163 on activated microglia/macrophages at the hematoma accumulation stage." (PMID 36792604, 2023). "Based on recent research involving both in vivo and in vitro phagocytic models, simvastatin can upregulate CD36 and increase the polarization of M2 microglia through the PPAR-γ pathway, thereby promoting hematoma absorption after ICH." (PMID 36970539, 2023). "The expression of CD36 and CD163 scavenger receptors on microglia/macrophages can be simultaneously increased through the PPAR-γ signaling pathway, effectively promoting endogenous hematoma absorption." (PMID 36970539, 2023). "Enhancing the upstream regulatory mechanism of CD36, including peroxisome proliferator-activated receptor γ (PPAR γ) and the nuclear factor erythroid 2–related factor 2 (Nrf2), is a potential approach to promoting CD36-mediated hematoma clearance." (PMID 35237132, 2022). "The importance of debris clearance by phagocytes is evident in rodents and humans lacking the scavenger receptor gene CD36, resulting in exacerbated injury and hematoma absorption in models of ICH." (PMID 26022493, 2015). "Although the duration of exogenous CDNF in blood circulation is relatively short, it still could increase the expression of CD163 and CD36 in the peri-hematoma area, implying that CDNF in the circulation could induce peripheral monocytes/macrophages to remove hematoma at the early stage of ICH." (PMID 36792604, 2023). "Furthermore, the soluble extracellulardomain of TREM2 impairs microglial/macrophage erythrophagocytosis by inhibitingvacuolar protein sorting 35-mediated CD36 recycling and promoting lysosomaldegradation of non-recycled CD36, ultimately delaying hematoma clearance andworsening neurological deficits." (PMID 41504200, 2025).
colon carcinoma (19 papers, 2013 to 2026). "The expression of both LPL and CD36, FA transporter, is primarily controlled by the peroxisome proliferator-activated receptor γ (PPARγ), a nuclear receptor that is frequently mutated or deregulated in colon cancer cells." (PMID 34206240, 2021). "Subsequently, we investigated CD36 expression in 39 pairs of human colon cancer samples using immunohistochemistry (IHC)." (PMID 36556492, 2022). "Our findings revealed a significant elevation in the levels of both FFA transporters in high-grade CRC tissues, which aligns with previous reports indicating that CD36 and FABP4 play a role in promoting colon cancer metastasis and are associated with a poor prognosis." (PMID 38245780, 2024). "CD36 regulates cell-attachment-to-extracellular matrix attachment, stromal cell fate, TGFβ activation, and immune signaling, which is an early marker of cancer invasion and metastasis in breast, prostate, ovarian, liver, and colon cancer." (PMID 35572595, 2022). "Presently, the status of CD36 in colon cancer remains inconsistent and it may require further investigation." (PMID 34206240, 2021). "For example, it can be expected that in vivo, colon cancer metastatic cells could also increase FA import from metastatic niche and consequently also PL production, e.g. through CD36 FA transporter up-regulation." (PMID 31999740, 2020). "CD36 expression might decrease stromal vascularization which contributed to better prognosis of colon cancer." (PMID 33102231, 2020). "Next, we investigated the clinical relevance of CD36 expression in a tissue microarray (TMA) consisting of 90 pairs of human colon cancer samples by immunohistochemistry (IHC), and finally 81 samples with visible tumor epithelium were included for following analysis." (PMID 31484922, 2019). "Only eight genes (UCN, TRIM, RBCK1, TPM2, CD36, NMB, PPARGC1A, and LGALS4) significantly affected the OS in patients with colon cancer (P < 0.05)." (PMID 35572595, 2022). "The fibroblasts and myofibroblasts were visualized by anti-human RGS5, decorin, podoplanin/gp36, CD36, α-SMA, and HHIP antibodies in colon mucosa and colon cancer tissues." (PMID 36463319, 2022). "Interestingly, lower expression of a number of genes (GREM1, LOX, TNFAIP6, CD36, and EDNRA) predicted better prognosis in both ovarian and colon cancers." (PMID 23536776, 2013). "A number of genes such as CCL20, CD36 and IL18RAP individually showed significant correlations with clinical variables in colon cancer such as tumor stage (T1 to T4), lymph node status (N0 to N2), metastasis (M0 or M1), pathological grade (G1 to G4) and Duke stage (A to D)." (PMID 23536776, 2013). "In our study, based on the colon cancer immune gene datasets, we used WGCNA to identify 21 immune-related hub genes affecting patients’ OS and constructed IRGPI based on 8 independent OS prognostic factors (UCN, TRIM58, RBCK1, TPM2, CD36, NMB, PPARGC1A, and LGALS4)." (PMID 35572595, 2022). "In contrast to FA synthesis genes, we found no upregulation of CD36 in the present study, which seems to support the hypothesis that colon cancer cells increase their FA content primarily via increased FA synthesis." (PMID 34206240, 2021).